RHOA (ras homolog family member A)
Diseases named in the same sentence as RHOA in open-access papers (continued):
Sharing a sentence is not in itself a finding about the gene and the disease.
gastric cancer (continued). "Similarly, Y42 mutations in RHOA, drivers of gastric cancer (GC), have been correlated with the creation of an immunosuppressive TME." (PMID 39596815, 2024). "Another protein identified to interplay with CSCs in a gastric cancer subtype (diffuse gastric cancer) is RhoA, a member of the Rho GTPase family, being involved in varied cellular functions such as proliferation and survival." (PMID 38139085, 2023). "Diffuse-type and, in particular, the GS molecular subtype of gastric cancer are also enriched for CLDN18-ARHGAP fusions, which seem to be mutually exclusive with RHOA and CDH1 mutations." (PMID 36812376, 2023). "Low concentrations of bupivacaine (10–50 mM) reduced migration of gastric cancer cells via the Ras homolog gene family member A (RhoA) and myosin light chain (MLC) pathways." (PMID 35252243, 2022). "In conclusion, our experiment found that both apatinib and an HSD not only elevated blood pressure in a gastric cancer mouse model through the RhoA/ROCK signaling pathway but also promoted vascular remodeling and left ventricular hypertrophy." (PMID 35811723, 2022). "The diffuse subtype which represents a small minority of gastric cancer, is genomically stable and associated with decreased expression of CDH1 (E-cadherin), higher expression of RhoA and prominent mesenchymal features, thus resulting in tumor aggressiveness." (PMID 35203450, 2022). "In gastric carcinoma, microenvironmental lymphocytes secrete Wnt5a to stimulate the proliferation of malignant cells by activating RhoA." (PMID 35210425, 2022). "Similar results were reported in breast and gastric cancer cells, where it was seen that Nrf2/Keap1 promoted cell migration by upregulating the RhoA/ROCK1 pathway." (PMID 33441941, 2021). "Taken together, miR-4646-5p/PHD3/HIF1A axis upregulates RhoA transcription and the RhoA activation can be triggered by miR-4646-5p/ABHD16A-mediated lipid metabolite lyso-PS accumulation in gastric cancer cells." (PMID 33875796, 2021). "Previous studies have shown that E-cadherin missense mutations associated with diffuse gastric cancer can induce an increase in RhoA activity, resulting in the proliferation and movement of gastric cancer cells." (PMID 34422902, 2021). "In another report, Wnt5a promoted cell migration via the PI3K/AKT/GSK3b/RhoA signaling pathway in gastric cancer." (PMID 34794402, 2021). "The activation and up-regulation of RhoA synergistically promote gastric cancer metastasis through LIMK/cofilin signaling." (PMID 33875796, 2021). "RhoA activity also has a positive correlation with Piezo1 activation, total RhoA is decreased in Piezo1 knockdown gastric cancer cells." (PMID 33994356, 2021). "In this study, we identified a gastric cancer biomarker, termed the “regulation of RhoA activity panel” (RRAP)." (PMID 33288739, 2020). "Upregulation of NORAD promoted gastric cancer progression by activating the RhoA/ROCK1 axis, which correlated with poorer prognosis." (PMID 33292272, 2020). "According to previous reports, RhoA expression is correlated only with N category (the absence or presence and extent of regional lymph node metastasis) and lymphatic invasion in gastric cancer patients." (PMID 31976530, 2020). "It is worth considering that, in gastric cancer cells, RhoA promotes cell proliferation and RhoC stimulates cell migration and invasion, while RhoB functions contrary to RhoA and/or RhoC." (PMID 32831016, 2020). "Lentiviruses packaged with this plasmid and appropriate guide RNAs (gRNAs) successfully knocked out the genes RhoA, Gli1, and Gal3 in human gastric cancer cell lines." (PMID 32053639, 2020).
gastric cancer (continued). "RhoA is a member of the RHO family GTPases and is associated with essential functions in gastric cancer." (PMID 33288739, 2020). "The knockdown of CNTN1 reduced cell migration and suppressed activation of RhoA and phosphorylation of p115 Rho guanine nucleotide exchange factor (RhoGEF, a RhoA activator) in gastric cancer." (PMID 33194679, 2020). "First, we explored literature regarding RHOA, in gastric cancer, in PubMed, using the search terms, “RHOA,” “expression,” and “cancer,” as of March 6, 2018, resulting in 1,536 articles." (PMID 31156701, 2019). "To determine the effects of RHOA mutations in vivo, we introduced WT, Y42C, and Y42S RHOA into the MKN74 gastric cancer cell line, which originally has WT-RHOA." (PMID 31485674, 2019). "Despite its poor signaling properties in recombinant cell lines, GPR1 was indeed demonstrated to signal through the RhoA/Rock cascade and to mediate part of the effects of chemerin on the migration and invasion properties of gastric carcinoma cells." (PMID 31803622, 2019). "ArhGEF28 interacts with RHOA which was found to be overexpressed in several cancers such as prostate cancer, gastric cancer and chronic myeloid leukemia." (PMID 30001383, 2018). "Down-regulation of PI3K/Akt/GSK3β signaling in gastric cancer cells suppresses Wnt5a-induced activation of RhoA and cell migration." (PMID 29213214, 2017). "The top perturbed pathways in gastric cancer included focal adhesion and adherens junction, in which RHOA gene and any other differentially expressed genes we detected participated in these biological processes." (PMID 29050278, 2017). "The RhoA protein prohibits apoptosis and promotes proliferation of incubatory SPCA1 lung cancer cells, and downregulation of RhoA suppresses the neoplastic overgrowth in Asian gastric cancer." (PMID 29108281, 2017). "Taken together, these findings demonstrate that RhoA function is necessary for CD24-mediated EGFR stability in gastric cancer SGC-7901 cells." (PMID 26830684, 2016). "Expectedly, NKX6.3 significantly decreased the protein expression of RhoA, Cdc42, p-Rac1/Cdc42, and Rac1/2/3 in gastric cancer cells." (PMID 27333045, 2016). "In summary, we demonstrate involvement of the oncogenic signal mediator RHOA, in gastric cancer, likely via EMT-related cytoskeletal remodeling necessary for cell motility and changes in morphology." (PMID 27806312, 2016). "Expression of CTGF is known to be induced by RhoA signaling and it is over-expressed in many types of cancers, including head and neck squamous cell carcinoma, pancreatic cancer, gastric cancer, and in pre-B acute lymphoblastic leukaemia." (PMID 27600078, 2016). "IL-6 induces AGS gastric cancer cell invasion via activation of the cellular-Rous sarcoma/ras homolog family member A (RhoA)/Rho-associated, coiled-coil-containing protein kinase signaling pathway, and RhoA expression may be a potential prognostic factor in gastric adenocarcinoma patients." (PMID 25788990, 2015). "IL-6 was shown to induce cell invasion via activation of c-Src/RhoA/ROCK signalling in a gastric cancer cell line." (PMID 25350954, 2014). "In conclusion, the expression of ST3GAL4 leads to SLex antigen expression in gastric cancer cells which in turn induces an increased invasive phenotype through the activation of c-Met, in association with Src, FAK and Cdc42, Rac1 and RhoA GTPases activation." (PMID 23799130, 2013). "Overall, our study showed that tumor cell invasion is induced by SLex expression on gastric cancer cells through the activation of c-Met in association with downstream signaling effectors Src, FAK and RhoA GTPases activation." (PMID 23799130, 2013). "We have previously shown that LPA, a phospholipid which acts through G protein coupled receptors and is known to activate RhoA, promotes gastric cancer cell invasion via NET1." (PMID 23945136, 2013).
gastric cancer (continued). "Transforming growth factor-β1 significantly upregulated the active form of RhoA in scirrhous gastric cancer cell lines, OCUM-2MLN (P=0.008) and OCUM-12 (P=0.007), when compared with control." (PMID 20145621, 2010). "In conclusion, TGFβ signalling stimulated the EMT and invasion ability of scirrhous gastric cancer cells through regulation of RhoA, myosin, ZO-2, and E-cadherin." (PMID 20145621, 2010). "Transforming growth factor-β1 significantly upregulated active RhoA and phospho-myosin of scirrhous gastric cancer cells." (PMID 20145621, 2010). "It is therefore likely that elevated levels of Net1 in gastric cancers favours tumour proliferation and invasion through RhoA activation." (PMID 16552434, 2006). "RHOA is a key participant, suggesting that anoikis maybe a promising target during the pathological process of the gastric cancer." (PMID 39286778, 2024). "Moreover, the PI3K-β inhibitor GSK2636771 decreased FFA production in RHOA-mutant human gastric cancer cells, thus limiting lipid uptake and metabolism in Tregs and suppressing their accumulation and function." (PMID 35948909, 2022). "Notably, RhoA was reported to facilitate the EMT process in gastric cancer and esophagus cancer; however, the association between EMT and RhoA is unclear in PC." (PMID 35256884, 2022). "Y27632, a selective small inhibitor of both ROCK1 and ROCK2, was combined with apatinib, and its efficacy was evaluated, wherein it can reduce hypertension induced by apatinib treatment in gastric cancer mice and weaken the activation of the RhoA/ROCK pathway by apatinib and a high-salt diet (HSD)." (PMID 35811723, 2022). "ABHD16A, as an emerging phosphatidylserine-specific lipase, involves in lipid metabolism leading to lysophosphatidylserines (lyso-PSs) accumulation, which stimulates RhoA and downstream LIMK/cofilin cascade activity through GPR34/Gi subunit, thus causes metastasis of gastric cancer." (PMID 33875796, 2021). "Some studies showed that sodium channel blockade contributed to the anticancer activity of LAs, but these studies also demonstrated that bupivacaine inhibited the migration of gastric cancer cells via the sodium-independent channel blocker RhoA and NET1 inhibition." (PMID 34950031, 2021). "In addition, miR-4646-5p/PHD3/HIF1A signaling can also up-regulate RhoA expression and synergistically promote gastric cancer cell invasion and metastasis." (PMID 33875796, 2021). "In gastric cancer, the upregulation of RhoA also enhances tumor invasion and metastasis." (PMID 34627383, 2021). "Namely, miR-4646-5p feedback promotes Abhd16a mRNA transcription and expression of ABHD16A protein, involving in lipid metabolism to cause lyso-PS accumulation, thus stimulates activation of GPR34 receptor to trigger RhoA/LIMK/cofilin signaling in fueling gastric cancer metastasis." (PMID 33875796, 2021). "Second, the panel used in the present study lacked several genes that are frequently mutated in gastric cancer such as RHOA and ARID1A." (PMID 33027286, 2020). "Moreover, RhoA is hyperactivated in gastric cancer tissues and cell lines, and is crucial for the cell cycle G1-S transition." (PMID 32392742, 2020). "RhoA-mediated Fbxw7 regulates the apoptosis of tumor cells and other phenotypes in gastric cancer." (PMID 32831016, 2020). "Mutations in “regulation of RhoA activity pathway” gene set may be involved in the prognosis and therapeutic prediction of gastric cancer through their effect on RhoA and its effector molecule activity." (PMID 33288739, 2020). "Furthermore, altered RhoA signaling has been reported in gastric cancers, especially in the diffuse type gastric cancer." (PMID 33288739, 2020). "Based on the pathway changes of RhoA activity, we developed a statistically optimized gene subset as a biomarker by applying a genetic algorithm to a training gastric cancer cohort obtained from the gastric cancer dataset of TCGA." (PMID 33288739, 2020).
gastric cancer (continued). "Furthermore, GSEA analyses carried out between low and high FBXW5 samples supported the pro-metastatic role of FBXW5 as high FBXW5 samples were found to be enriched in gene sets related to metastasis, RhoA signaling and advanced stage gastric cancer." (PMID 31213005, 2019). "Gene Set Enrichment Analysis (GSEA) was carried out between low FBXW5 samples and high FBXW5 samples, whereby the high FBXW5 samples were found to be enriched in gene sets related to metastasis (p-value < 0.001), RhoA signaling (p-value < 0.001) and advanced stage gastric cancer (p-value < 0.001)." (PMID 31213005, 2019). "We also found that mRNA expression levels of CDH1, CDKN1A, and EP300 were significantly reduced while those of RhoA, ROCK1, ROCK2, PIK3CA, and CCND1 were significantly increased in gastric cancers with reduced or loss of NKX6.3 expression compared to those in NKX6.3 positive cases." (PMID 30514953, 2018). "In addition, expression levels of CDH1, CDKN1A, and EP300 were reduced while expression levels of RhoA, ROCK1, ROCK2, PIK3CA, and CCND1 were increased in gastric cancer tissues with reduced or loss of NKX6.3 expression." (PMID 30514953, 2018). "Blockade of ITGA2 by the antibody may induce apoptosis through RhoA-p38 MAPK signaling pathway in gastric cancer cells, consistent with previous reports that the RhoA and p38 MAPK are rapidly activated, upon cellular cholesterol depletion, to induce apoptosis." (PMID 29743821, 2018). "Next, we determined the expression of NKX6.3, E-cadherin, N-cadherin, β-catenin, p-GSK3βY216, CLND1, RhoA, Cdc42, Rac1/2/3, Snail, Slug and Vimentin proteins in 7 gastric cancer tissues at different TNM stages and compared with expression in non-tumorous gastric mucosal tissues." (PMID 27333045, 2016). "In addition, we noticed that the effect of CD24 on EGFR stability was mediated by RhoA activity in SGC-7901 gastric cancer cells." (PMID 26830684, 2016). "RhoA colocalized to NF-κB P50 in both cytoplasm and nucleus in human gastric cancer cells." (PMID 27043630, 2016). "However, when we analyzed the role of RhoA protein on EGFR stability in gastric cancer cells, we observed that the inhibition of RhoA impaired EGFR expression and active RhoA markedly increased EGFR expression." (PMID 26830684, 2016). "In our previous studies LPA activation of RhoA was shown to be mediated via NET1 in gastric cancer." (PMID 23945136, 2013). "Although not explored in the current study, our ongoing efforts will define whether LPA drives RhoA activation in OAC cells as it does in gastric cancer cells." (PMID 23945136, 2013). "The EMT of scirrhous gastric cancer cells induced by TGFβ signalling might be mediated by the regulation of RhoA, myosin, ZO-2, and E-cadherin." (PMID 20145621, 2010). "However, Ki26894 significantly inhibited the active RhoA induced by TGF-β1 in scirrhous gastric cancer cell lines, OCUM-2MLN (P=0.047) and OCUM-12 (P=0.029)." (PMID 20145621, 2010). "Furthermore, Ki26894 inhibited the upregulation of active RhoA and phospho-myosin and inhibited the downregulation of E-cadherin and ZO-2 expression in scirrhous gastric cancer cells." (PMID 20145621, 2010). "Invasion by scirrhous gastric cancer cells may be inhibited by a TβR inhibitor through regulation of RhoA, myosin, E-cadherin, and ZO-2 expression." (PMID 20145621, 2010). "In this study, TGF-β1 significantly upregulated active RhoA of scirrhous gastric cancer cells." (PMID 20145621, 2010). "Lysophosphatidic acid was shown to increase the levels of active RhoA in AGS gastric cancer cells." (PMID 18827818, 2008). "Particularly, these findings agree with previous data from gastric cancer cells, in which suppression of PI3K/AKT by the PI3K inhibitor LY294002 or silencing AKT leads to decreased Wnt5-induced GSK-3 phosphorylation, which further causes reduced RhoA-dependent cell migration and actin remodeling." (PMID 40940769, 2025). "•SC might as a RhoA-directed therapeutic for gastric cancer." (PMID 40746849, 2025).
gastric cancer (continued). "Therefore, we propose that in the treatment of gastric cancer, the combination of RhoA/ROCK1 inhibitors may enhance the tumor‐killing effect of OXA." (PMID 39392399, 2024). "Contradictorily, it was also reported that RACGAP1 in gastric cancer could inactivate Rac and RhoA." (PMID 39858398, 2024). "The goals of this study were to apply gastric cancer modeling technology to simulate the real in vivo environment to explore whether the RhoA/ROCK signaling pathway is involved in the occurrence of this type of hypertension and whether ROCK inhibitors have therapeutic effects." (PMID 35811723, 2022). "In this study, in vivo experiments were performed to explore whether the RhoA/ROCK signaling pathway is part of a possible mechanism of apatinib in the treatment of gastric cancer-induced hypertension and the impairment of vascular remodeling and left ventricular function." (PMID 35811723, 2022). "Moreover, FBXW7 could inhibit the EMT by down-regulating the RhoA signaling pathway in gastric cancer." (PMID 28716020, 2017). "Although MSI-H gastric cancers are hyper-mutated, MSS gastric cancers also possess a high frequency of genetic alterations such as CDH1, RHOA, HER2, EGFR, VEGFR, MET, and FGFR2, all of which may directly or indirectly affect the MAPK and PI3K/Akt survival pathways." (PMID 29137273, 2017). "To determine whether NKX6.3 reduces gastric cancer cell migration through down-regulation of the Rho-GTPase family, we examined the expression of CD2-associated protein (CD2AP), RhoA, Cdc42, p-Rac1/Cdc42 and Rac1/2/3 proteins, in AGSNKX6.3 and MKN1NKX6.3 cells." (PMID 27333045, 2016). "It was reported that gastric cancer cell invasion could be induced via activation of the RhoA/ROCK pathway by IL-6, and RhoA and RhoC siRNA gene therapy mediated by adenovirus has been suggested as useful for inhibiting the growth and invasion of human gastric carcinoma via the PI3K/Akt pathway." (PMID 25238232, 2014). "NET1, a RhoA guanine exchange factor, is up-regulated in gastric cancer (GC) tissue and drives the invasive phenotype of this disease." (PMID 21284875, 2011). "In gastric cancer, YAP promotes ARHGAP29 expression, which, in turn, inhibits the RhoA-LIMK-cofilin pathway and destabilizes F-actin, thereby promoting gastric cancer cell migration." (PMID 39744435, 2025). "Retraction: Jun Xiao, Hao Lai, Sheng-Hong Wei, Zai-Sheng Ye, Fu-Sheng Gong, Lu-Chuan Chen (2019), lncRNA HOTAIR promotes gastric cancer proliferation and metastasis via targeting miR-126 to active CXCR4 and RhoA signaling pathway." (PMID 38695659, 2024). "A micro-G-protein molecule with GTPase activity in the Ras superfamily, RhoA can activate signal transducer and activator of transcription 3 (STAT3) to promote the formation of various tumors, including breast, gastric cancer and colorectal cancer (CRC)." (PMID 38717722, 2024). "Referring to mining of the GEO database, the GSE26309 dataset was divided into AGS gastric cancer cells Control group, RhoA activator group (LPA), RhoA GEF exchange factor (NET1) knockdown group (shNET1), NET1 knockdown and RhoA activator group (shNET1-LPA)." (PMID 37670284, 2023). "The elevated lyso-PS contributed to activation of RhoA through GPR34/Gi, thus resulting in gastric cancer metastasis." (PMID 33875796, 2021). "To conclude, it substantiates CD73 as a target for treatment of gastric cancer metastasis and verifies RICS as an intracellular functional molecule linking CD73/adenosinergic signaling switching to RhoA/LIMK/cofilin pathway." (PMID 32205841, 2020). "Similarly, Gastrokine 1’s inhibition of gastric cancer progression may also be dependent on RhoA." (PMID 32831016, 2020). "Ectopic expression of RhoA promotes proliferation and RhoC overexpression enhances motility and invasiveness of SGC7901 and AGS human gastric cancer cell lines, while RhoB overexpression suppresses these malignant phenotypes." (PMID 32392742, 2020).